SFRP1 (secreted frizzled related protein 1)
Diseases named in the same sentence as SFRP1 in open-access papers (continued):
Sharing a sentence is not in itself a finding about the gene and the disease.
tumor (continued). "In contrast, another commonly reported CCRCC hypermethylated gene, SFRP1, has 3 of its 5 associated probes within the predicted CpG island and all three demonstrate frequent tumor-specific hypermethylation." (PMID 24454902, 2014). "Bearing in mind that SFRP1 is a known tumor suppressor gene this association gives insight into a novel putative BDNF function." (PMID 25036590, 2014). "High expression of WIF1 was significantly associated with big tumor diameters and deep invasion, while loss of SFRP1 expression was significantly associated with the left lesion site, deep invasion, and high TNM stage." (PMID 24949429, 2014). "Lastly, age itself was modestly associated with the methylation status at the SFRP1 locus in the tumor samples tumor samples (p = 0.084)." (PMID 22701537, 2012). "In our data, it was up-regulated in ccRCC and predicted to target SFRP1, a known regulator of the Wnt signaling pathway and a tumor suppressor gene whose loss has been observed in a majority of RCC patients." (PMID 20420713, 2010). "Based on its widespread loss, interest in testing the effects of sFRP1 treatment in tumor models has been high." (PMID 19473496, 2009). "SFRP1 expression in bladder tumors is associated with lower tumor grades." (PMID 40635786, 2025). "However, the proportion of CSCs in tumor tissue increased in Sfrp1-deficient mice in the early phase." (PMID 38625488, 2024). "SFRP1 has been suggested and examined as a possible tumor suppressor gene, as silencing may predispose to neoplastic progression." (PMID 34830873, 2021). "In clinical tumor tissue samples, high miR-1260b expression was detected in tumors of non-responding patients treated with taxane-based chemotherapy and was associated with low SFRP1 expression and poor prognosis." (PMID 33224874, 2020). "In contrast, drugs that affect the Wnt pathway upstream of APC truncation have not been tested for use in cancers harboring APC mutations, even though one of these agents, Secreted Frizzled-Related Protein 1 (sFRP1), was found effective in preclinical tumor models." (PMID 28708837, 2017). "Taken together, these observations may provide insight into the role SFRP1 plays in tumor susceptibility." (PMID 28687085, 2017). "The loss of sFRP1 was associated with higher tumor stage and grade and shorter overall survival." (PMID 22325146, 2012). "Besides, significant association between increased tumor grade, stage or tumor recurrence and methylation of p14, SFRP1, APC, hMLH1 and p15 were observed in samples from Hong Kong." (PMID 21599969, 2011). "We therefore considered the possibility that the density or the functionality of the tumor-associated vessels might be impaired in sFRP1-expressing tumors." (PMID 19473496, 2009). "This could be tumor cell intrinsic, resulting from downregulation of WNT signaling, and/or extrinsic via secreted sFRP1 effects on tumor-associated cells; both possibilities were tested." (PMID 19473496, 2009). "Interestingly, stratifying the data by patient group and adjusting for age showed that the male-associated increased methylation of WIF1 and SFRP1 was specific for the neoplasia-free subjects only." (PMID 18542073, 2008). "Sfrp1 has been shown to induce apoptosis in numerous tissues and loss of Sfrp1 significantly impacts apoptotic related gene expression as well as activity suggesting a causative role for reduced Sfrp1 in premalignant breast changes leading to tumor progression." (PMID 24885183, 2014). "Thus, we initially hypothesized that knockdown of SFRP1 might result in increased Wnt signaling activity, thereby promoting tumor-associated properties of cells." (PMID 25033833, 2014). "In vitro and in vivo experiments confirmed that SFRP1-producing CAFs promote tumor stemness and epithelial-mesenchymal transition (EMT)." (PMID 40225580, 2025).
tumor (continued). "In our study, we investigated the correlation between SFRP1-5 and the tumor immune infiltration levels of five major immune cell types: B cells, CD8 + T cells, CD4 + T cells, macrophages, and neutrophils." (PMID 39729237, 2025). "Crucially, our strategy in SFRP1-OE targets a transition over a stage, enabling an effective disruption of tumor dynamics." (PMID 40770193, 2025). "Applying our GBM population models revealed that the stark reduction in tumor growth rate resulted from a decrease in activation rate, pinpointing the action of SFRP1 to the Q–A transition." (PMID 40770193, 2025). "Mechanistically, our study demonstrated that SFRP1-producing CAFs interact with cancer cells via the SFRP1-FGFR2-HIF1 signaling axis to drive both tumor stemness and metastatic potential." (PMID 40225580, 2025). "The secretory protein SFRP1 from CFD+ iCAFs promoted tumor stemness and EMT activity, thereby leading to CRLM." (PMID 40225580, 2025). "The immunoprecipitation-mass spectrometry (IP-MS) workflow was performed to investigate how SFRP1 influenced tumor cells to promote metastasis." (PMID 40225580, 2025). "Overexpression of SFRP1 in tumor cells decreases BC cell viability and migration, reducing malignancy." (PMID 40635786, 2025). "Our results also demonstrate that the demethylation of SFRP1/2 can significantly suppress tumor cell proliferation and promote apoptosis." (PMID 39729237, 2025). "In tumor biology, SFRP1 is generally recognized for its tumor-suppressive functions, with its silencing or downregulation in PAAD associated with tumor progression and poor prognosis." (PMID 41595468, 2025). "Further supporting these observations, IHC analysis of human CRC tissues also confirmed high SFRP1 expression from stroma cells was positively correlated with tumor progression, underscoring its critical role in promoting metastasis." (PMID 40225580, 2025). "Strikingly, SFRP1-overexpression (OE) in tumor cells significantly improved overall survival in mouse PDXs, while scRNA-seq revealed that GBM cells were stalled in a quiescent astrocyte-like stage." (PMID 40770193, 2025). "While most studies have examined SFRP1 in tumor tissue or cell lines, recent research has demonstrated the utility of a cfDNA-based liquid biopsy approach for examining promoter hypermethylation of SFRP1 (phSFRP1) and assessing prognosis in patients with PDAC." (PMID 40492125, 2025). "Reduced expression of SFRP1 in tumor tissue has been proposed as a potential prognostic biomarker in several cancers, including PDAC." (PMID 40492125, 2025). "Secreted frizzled-related protein 1 (SFRP1) gene promoter methylation was also examined in tumor tissue samples." (PMID 40867261, 2025). "SFRP1, known as a tumor suppressor gene in most cancers, influences tumor development through epigenetic inactivation, which affects DNA methylation or miRNA-mediated transcriptional silencing." (PMID 39729237, 2025). "These alterations were reversed in the shFGFR2 and Echinomycin groups, suggesting SFRP1 promotes tumor stemness and metastasis through FGFR2 and HIF1 pathway." (PMID 40225580, 2025). "Taken together, these results suggest secretory protein SFRP1-producing CAFs promotes tumor stemness and EMT activity, thereby contributing to tumor progression." (PMID 40225580, 2025). "Together, these findings demonstrate that CAF-derived SFRP1 played a critical role in facilitating tumor stemness and metastasis in CRLM, providing valuable insights into its potential as a therapeutic target." (PMID 40225580, 2025). "To validate the relationship between SFRP1/2 methylation and immune cell infiltration, we used the TISIDB website and found a positive correlation between SFRP1/2 and the expression of tumor-infiltrating lymphocytes in CRC." (PMID 39729237, 2025). "SFRP1, part of the secreted frizzled-related protein family, and modulating Wnt signaling, is dysregulated in several human tumor types." (PMID 40034439, 2025).
tumor (continued). "Using ptalign, we compare inter-tumor gene expression dynamics in 51 GBMs to the healthy counterpart, identifying the secreted Wnt antagonist SFRP1 as recurrently dysregulated." (PMID 40770193, 2025). "It has been reported that the promoter methylation levels of AKT3, CD147, LINE1, MAGEA1, RASSF1A, and SFRP1 were considerably correlated with OS, tumor volume, and cancer properties." (PMID 38206300, 2024). "Using these Sfrp1-overexpressing cells, we performed tumor transplantation experiments and found that tumor growth was promoted in Sfrp1-overexpressing cells, and tumor weight was markedly increased (p < 0.05)." (PMID 38625488, 2024). "In this study, we clarified the effects of Sfrp1 on tumor tissues and analyzed its interactions with tumor blood vessels." (PMID 38625488, 2024). "While Sfrp1 was expressed in many APJ-positive veins during this period, only approximately 8% of tumor vessels showed Sfrp1 expression." (PMID 38625488, 2024). "To determine the localization of Sfrp1, an angiocrine factor critical for angiogenesis, in tumor tissues, we evaluated its expression." (PMID 38625488, 2024). "Real-time PCR results from tumors of Sfrp1 KO mice showed that the expression of Wnt signaling target genes significantly decreased in the late stage of tumor growth." (PMID 38625488, 2024). "We investigated the localization of Sfrp1 in tumors and found that it is expressed in some tumor vessels." (PMID 38625488, 2024). "The results of this study suggest that Sfrp1 is expressed in a portion of tumor vessels in the CSC niche, indicating that the blood vessels within the tumor are not homogeneous but rather heterogeneous." (PMID 38625488, 2024). "A similar transplantation experiment was performed using MC38 cells, and tumor growth was suppressed in Sfrp1 KO mice compared with that in WT mice (p < 0.01)." (PMID 38625488, 2024). "In the early stages of tumor transplantation, the expression of Wnt signaling target genes was observed in the CCs of Sfrp1 KO mice." (PMID 38625488, 2024). "This suggests that Sfrp1, an angiocrine factor produced by the tumor vascular niche, is involved in Wnt signaling-mediated mechanisms in tumor tissues." (PMID 38625488, 2024). "Within the realm of known WNT antagonists, the secreted frizzled-related protein 1 (SFRP1) frequently experiences downregulation across various cancer types, implying its tumor-suppressive functions." (PMID 38390281, 2024). "In this study, we demonstrated that Sfrp1, an angiocrine factor produced by tumor blood vessels in the tumor environment, is involved in tumor growth." (PMID 38625488, 2024). "In contrast, the expression of Wnt signaling target genes was significantly decreased in the late stage after tumor inoculation in the CCs of Sfrp1 KO mice." (PMID 38625488, 2024). "Previous studies have indicated the role of miR-1-3p as a tumor suppressor in different cancers through different mechanisms, such as upregulating SFRP1, repressing E2F5 and PFTAIRE protein kinase 1, and modulating BDNF and TrkB." (PMID 38793064, 2024). "Flow cytometry analysis indicated that CSCs were maintained in the early tumor growth phase in the Sfrp1 knockout (KO) mouse model of tumor-bearing cancer." (PMID 38625488, 2024). "All five clusters of tumor epithelial cells were indeed observed in AM samples by using marker genes (HLA-B for IR, SFRP1 for BR, KRT13 for ED, ODAM for TD, LAMC2 for TD, and KI67 for CC)." (PMID 38424060, 2024). "Further analysis showed a significant increase in the expression of SFRP1 in both knockout groups, a gene that has been shown in our previous studies to play a tumour suppressor role in CCA." (PMID 38050190, 2023). "A core CpG island was identified that exhibited abundant tumor DNA methylation and anti-correlation of SFRP1 mRNA expression." (PMID 36765639, 2023).
tumor (continued). "AC tumour samples had a higher SFRP1 level than NT samples (p = 0.022), while the highest SFRP1 concentration was found in NSCLC samples from patients with clinical stage T4 cancer." (PMID 37999144, 2023). "Through transcriptome sequencing of CCA models with knockout of EZH2 and SUZ12, respectively, we identified SFRP1, a gene that plays a tumour suppressor role in CCA." (PMID 38050190, 2023). "Over‐expression of SFRP1 can significantly inhibit the proliferation of tumour cells by negatively regulating β‐Catenin." (PMID 38050190, 2023). "Secreted frizzled‐related protein 1 (SFRP1) has been identified as a tumour suppressor gene that is commonly downregulated in human cancers." (PMID 38050190, 2023). "On the other hand, the concentration of SFRP1 was insignificantly higher in SCC tumour samples and insignificantly lower in LCC tumour samples compared to NT samples." (PMID 37999144, 2023). "The ratio of mouse liver weight to body weight showed a significantly decreased tumour load in A/N+ Sfrp1 compared to A/N+V mice." (PMID 38050190, 2023). "In this study, a significantly higher concentration of SFRP1 was found in the tumour samples compared to NT samples among patients with adenocarcinoma." (PMID 37999144, 2023). "From a mechanistic point of view, SFRP1 decreased expression in tumor tissue compared to normal breast tissue seemed to be mediated by its promoter, methylation (p-value < 0.0001)." (PMID 37190179, 2023). "Secreted frizzled related protein-1 (SFRP1) is a tumor suppressor gene that mainly functions as an inhibitor of the oncogenic Wnt/ß-catenin pathway." (PMID 37333823, 2023). "Histological analysis showed positive staining for cytokeratin 19 in both A/N+Sfrp1 and A/N+V transfected induced tumours, and histochemical staining further demonstrated the overexpression effects of Sfrp1." (PMID 38050190, 2023). "H&E staining showed a significant increase in the number of tumour lesions in A/N+Sfrp1 mice compared to A/N+V mice." (PMID 38050190, 2023). "Overexpression of SFRP4 in A2780 cells increases cisplatin sensitivity, while EOC transgenic mouse models overexpressing SFRP1 exhibit >50% reduced tumor volume compared to WT mice." (PMID 37123549, 2023). "Since SFRP1 has been found to be down-regulated in a number of human malignancies, it has been designated as a tumour suppressor gene." (PMID 35646102, 2022). "Inspiringly, we found miR-26a-5p regulated DNMT3A expression to remold DNA methylation pattern of SFRP1, therefore, modulated tumor growth and cancer stem cell-like properties via Wnt/β-catenin signaling pathway." (PMID 35860691, 2022). "SFRP1 was overexpressed in normal tissues compared to in tumor tissues, especially in patients in the early clinical stage and early T stage." (PMID 35892344, 2022). "In transgenic mouse models of FTC, a mechanism was found that advanced cancer in emasculated men was due to increased expression of tumor suppressor genes:GLIPR1 and SFRP1, resulting in increased tumor invasion of M1-macrophages and CD8 cells." (PMID 35479325, 2022). "Genes in the Wnt signaling pathway such as, WNT2 and WNT5A, were upregulated in tumor fibroblasts while SFRP1, an inhibitor of Wnt signaling was downregulated." (PMID 35999201, 2022). "Subsequent integrative molecular analyses have revealed, for the first time, the important role of SFRP1, a well-characterized member of the Secreted Frizzled-Related Protein family, which has been verified to be a tumor suppressor in various neoplasms." (PMID 35892344, 2022). "Our results revealed that miR-26a-5p acted as a tumor suppressor through targeting DNMT3A to upregulate SFRP1 via reducing DNMT3A-dependent DNA methylation." (PMID 35860691, 2022). "Our further studies clarified the role of some aberrantly methylated genes in tumor progression, such as ZNF154 (encoding zinc finger protein 154) and SFRP1 (encoding secreted frizzled related protein 1), which act as antioncogenes to inhibit NPC metastasis." (PMID 35410462, 2022).
tumor (continued). "It was found that the SFRP1 gene, as a potential tumor suppressor, was down-regulated by epigenetic alteration of SFRP1 protein expression." (PMID 35719392, 2022). "The promoter methylation levels of selected candidate genes (RASSF1A, DAPK1, SOX1, HOXA9, HIC1, SPARC, and SFRP1) were quantitatively evaluated by MethyLight in tumor DNA samples of patients with EOC." (PMID 34778370, 2021). "In the past, SFRP1 has been considered to be a tumor suppressor gene and possibly antagonistic to the wnt signaling pathway." (PMID 34222474, 2021). "The secreted frizzled-related protein 1 and 2 genes (SFRP1 and SFRP2) encode antagonists of the Wnt signaling pathway, acting as tumor suppressors." (PMID 33030559, 2021). "The correlation analysis of different clinical parameters and tumor characteristics revealed a significant correlation of reduced SFRP1 expression with the presence of mutant β-catenin." (PMID 32189106, 2020). "In this review, we discussed in great detail the dual roles of SFRP1 in cancers—as tumor suppressor and tumor promoter." (PMID 32074995, 2020). "The epigenetic silencing of SFRP1 was also significantly correlated with tumor stage and lymph node status." (PMID 32074995, 2020). "As a novel member of the SFRP family, SFRP1 has been confirmed to exert inhibitory effects on tumor cell growth, invasion, and chemoresistance." (PMID 33224874, 2020). "Overexpression of SFRP1 in HB cell lines diminished tumor cell proliferation, colony formation and migration potential." (PMID 32189106, 2020). "Overall, we detected a low SFRP1 gene expression in 62% (28/45) of cases and the median SFRP1 expression level was reduced in tumor tissue compared to normal liver, although the difference was not significant." (PMID 32189106, 2020). "The WNT antagonist, SFRP1, was also a tumor suppressor that regulates cell proliferation and blood vessel formation." (PMID 32832275, 2020). "Altogether, our results demonstrate that a restored SFRP1 expression has tumor-suppressive effects in HB cells by reducing the activity of the canonical WNT/β-catenin pathway." (PMID 32189106, 2020). "The distribution of SFRP1-methylated and -unmethylated cases in relation to the tumor type clearly showed that most of the HCC/TLCT samples displayed an enrichment of SFRP1 DNA methylation and that all tumors with a TERT mutation were SFRP1-methylated." (PMID 32189106, 2020). "From RNA-Seq analysis, we found that tumour suppressors such as Ccdc80, Itm2a, and Sfrp1 were significantly up-regulated by the combination treatment of vactosertib with nal-IRI/5-FU/LV compared to the control group and the nal-IRI/5-FU/LV group." (PMID 32076068, 2020). "Functional assay in numerous literatures provided further evidences supporting that some of the loci have close links with the modulation of tumor-suppressive mechanisms via regulation gene transcription (e.g., SFRP1 and WIF1)." (PMID 31959227, 2020). "In bone metastases from prostate primary tumor, overexpression of SFRP1 results in an osteolytic response of the tumor cells." (PMID 31947616, 2020). "First, SFRP1 profile expression between tumor and normal prostate tissues was obtained using GEPIA database." (PMID 32694934, 2020). "In line with studies in HCC and other tumor entities, a re-expression of SFRP1 inhibited tumor cell growth, colony formation and migration of HB tumor cells." (PMID 32189106, 2020). "The differences in gene expression between tumor and normal tissue were relatively small, but that of SFRP1 gene expression was larger." (PMID 32764696, 2020). "First, we performed in silico screening using databases and found SFRP1 is down-expressed in tumor samples with poor positive correlation between the expression of SFRP1 and ERG in PCa samples as expected." (PMID 32694934, 2020).